ACE (angiotensin I converting enzyme)
Diseases named in the same sentence as ACE in open-access papers (continued):
Sharing a sentence is not in itself a finding about the gene and the disease.
COVID-19 (continued). "Our study showed that the use of antibiotics, ACE inhibitors, PPIs, or HCQ/CQ at the time of hospital admission due to SARS-CoV-2 infection was more significantly associated with severe symptoms of COVID-19." (PMID 35572676, 2022). "The use of RAS inhibitors, including ACE inhibitors and angiotensin receptor blockers (ARBs) is controversial in COVID-19 patients." (PMID 35453563, 2022). "The strong positive correlation (r2 = 0.63–0.77) between the ACE2 serum levels and levels of cholecalciferol and its metabolites in our COVID-19 individuals confirms the expected role of ACE level in the disease severity." (PMID 36558489, 2022). "The relevance of the ACE/ACE2 balance in COVID-19 development and treatment has received much attention." (PMID 36553622, 2022). "MAPK14, ACE, TLR4, and MAPK8 genes are present in all the compounds, and these genes are associated with COVID-19 pathways." (PMID 36144690, 2022). "Prior treatments were similar in case of antiplatelets and statins, anticoagulants were more used by the COVID-19-positive patients (27.8% vs 9.2%; P = .009), while ACE inhibitors were less used (11.1% vs 44.4%; P = .001)." (PMID 35777044, 2022). "COVID-19 enters the brain by involving angiotensin-converting enzyme (ACE)-2 receptors present in the CNS." (PMID 35883527, 2022). "Our results also show a significant effect of diuretics and angiotensin-converting enzyme (ACE) inhibitors on reducing severe respiratory failure among COVID-19 patients." (PMID 36583016, 2022). "Anosmia and/or dysgeusia reported by some COVID-19 patients is a well-known side effect of ACE inhibitors." (PMID 35153624, 2022). "A small study has shown that ACE-inhibitors decrease IL-6 levels and peak viral load in COVID-19 patients which has led to a change in antihypertensive management in COVID-19 patients." (PMID 35548445, 2022). "The mechanism-based similarity between COVID-19 and RA is based on the angiotensin converting enzyme (ACE)-dependent pathway and the macrophage-dependent pathway." (PMID 35054471, 2022). "We have investigated sera of COVID-19 patients for their serum ACE activity using its substrate, the neuropeptide bradykinin (BK), as a reporter substance." (PMID 35330406, 2022). "In Asian populations, mortality rates and the presence of the D allele revealed the substantial positive connection, demonstrating that greater levels of ACE are harmful to COVID-19 patients." (PMID 36553622, 2022). "It is shown that COVID-19 is activated with renin-angiotensin system imbalance, which activates the classical arm (ACE/Ang II/AT1R) and leads to pulmonary injury, hematological alterations, and hyper-inflammatory state." (PMID 35356739, 2022). "It is possible to say that COVID-19 and RA have the same immunopathogenic mechanism driven by abnormal ACE/ACE2 activity." (PMID 35054471, 2022). "The shift to the alternative RAS axis was time dependent and increased with time, and the intrinsic ACE activity in severe COVID-19 was already low at hospitalization." (PMID 36418458, 2022). "Dexamethasone, which is now the standard of care in severe COVID-19, upregulates ACE and ACE2 and decreases morbidity and mortality." (PMID 35913134, 2022). "The impairment of the ACE/ACE2 ratio in coronavirus diseases is related to the pathological mechanism of COVID-19." (PMID 35889330, 2022). "ACE inhibitors and angiotensin receptor blockers have been shown to be effective in COVID-19, delaying SARS-CoV-2 binding by activating ACE2 and boosting angiotensin-1–7 availability." (PMID 35054471, 2022). "Two polymorphisms analyzed in our study, ACE rs4646994 and ACE2 rs2285666, are important regulators of the RAAS pathway, a physiological system implicated in COVID-19 susceptibility and severity." (PMID 35795626, 2022). "Recent studies have suggested the association of genetic polymorphisms of ACE and ACE2 with the case rate of COVID-19." (PMID 35250987, 2022).
COVID-19 (continued). "Patients in the severe COVID-19 group were the predominant users of antibiotics (88.6%), ACE inhibitors (29.8%), PPI (42.7%), and corticosteroids (14.5%)." (PMID 35572676, 2022). "Therefore, ACE D/I polymorphism could affect the clinical course of COVID-19." (PMID 34603503, 2021). "Considering studies of the ACE I/D polymorphism in human population genetics, the variant may in part underlie the biological factors contributing to individual race/ethnicity-related host response observed in the clinical manifestations and outcomes of COVID-19." (PMID 33390179, 2021). "There has been considerable controversy over the use of angiotensin receptor blocker (ARBs) like losartan and angiotensin-converting enzyme (ACE) inhibitors (which are mainly used in treatment of elevated blood pressure) in patients with COVID-19." (PMID 33850936, 2021). "In fact, in a retrospective study, a reduction in COVID-19–related mortality was observed in hospitalized individuals with hypertension who had been treated with ACE inhibitors or angiotensin receptor blockers compared to those not using any of these drugs." (PMID 33584343, 2021). "Randomized studies are requested to study the effect of treatment with action on the endothelium function such as Beta-blockers, ACE inhibitors, ARBs, and statins on the long COVID-19 symptoms." (PMID 34917659, 2021). "RNA sequence analysis has shown that plasma kallikrein and bradykinin precursors are expressed at increased levels and that degrading enzymes (e.g. ACE) are substantially downregulated in patients with COVID-19." (PMID 33693976, 2021). "The intragroup comparison showed that many immune-related pathways of different ACE expressions were significantly changed under the influence of COVID-19 compared with the healthy group." (PMID 35095487, 2021). "Different ACE genotypes are believed to be associated with development of acute respiratory distress syndrome and several studies have reported that the distribution frequency of ACE insertion/insertion (II) genotype might have a significant influence on COVID-19 mortality." (PMID 34834450, 2021). "Various trials currently listed in clinicaltrials.gov aim to include patients with COVID-19 and to test a treatment with angiotensin receptor blockers, ACE inhibitors, or Ang 1–7." (PMID 35498160, 2021). "Other studies showed slightly decreased ACE activity in the blood of patients with moderate to severe acute respiratory failure due to COVID-19 and higher Ang II levels in survivors than in non-survivors of COVID-related ARDS." (PMID 35498160, 2021). "COVID-19 uses ACE to enter type II pneumocytes cells to induce ACE2 internalization and shedding, resulting in the occurrence and development of ARDS." (PMID 34941025, 2021). "Moreover, comparing with the conventional ACE-inhibitory drugs, these peptides are of natural origin and do not produce toxic side effects when overused, which might help reduce the risk of traditional drugs when treating COVID-19." (PMID 33671652, 2021). "Although there were a lot of conflicting reports on the use of ACE2 inhibitors on COVID-19 patients, our docking results showed fascinating binding interaction between the ACE inhibitors and the spike protein." (PMID 34458381, 2021). "There is a current controversy concerning the usage of ACE inhibitors and AR blockers in patients with COVID-19." (PMID 34554559, 2021). "The team has also demonstrated its capacity in plant-based heterologous protein expression and the effort toward COVID-19 by producing ACE-Fc and SARS-CoV-2 neutralizing antibodies B38 and H4." (PMID 34579229, 2021). "COVID-19 apparently causes, at least in part, imbalances in the RAS by negativelyregulating ACE2, thereby exacerbating the ACE/AngII/AT1R axi53, and producing predominantly proinflammatory effects." (PMID 33704348, 2021).
COVID-19 (continued). "Meanwhile, reduced risk of severe COVID-19 symptom is found associated with patients that has been prescribed with ACE inhibitor drugs, indicating the possible protective effect of ACE2 activity inhibition during the clinical treatment of COVID-19." (PMID 34867400, 2021). "Suppression of ACE2 and activation of ACE in alveolar tissues and joints share an identical mechanistic pathway of disease pathogenesis in both COVID-19 and RA, respectively." (PMID 34943795, 2021). "There have been studies that evaluated the role of angiotensin-converting enzyme (ACE) inhibitors (ACEi) and angiotensin receptor blockers (ARBs) in treating patients with COVID-19." (PMID 34277195, 2021). "A recent study showed that plasma ACE2 activity is increased in COVID-19 patients treated with ACE inhibitors." (PMID 34086837, 2021). "High-serum ACE and ACE2 are known risk factors for CVD and, as revealed more recently, COVID-19 severity." (PMID 34751382, 2021). "The resulting model can be used to assess the extent to which ACE inhibitors and ARBs promote the internalization of SARS-CoV-2 and predispose the host to more severe COVID-19." (PMID 34198530, 2021). "According to Sriram and Insel, the imbalance in the action of ACE2 and ACE is one of the main culprits of COVID-19 pathobiology." (PMID 34769093, 2021). "Strikingly, more biomarkers are involved in the severity and death of COVID-19 patients within the higher ACE expression subgroup, suggesting that higher ACE expression is related to distinct symptoms of COVID-19." (PMID 35095487, 2021). "The possible benefit of ARBs for COVID-19 is also supported by multiple retrospective studies showing that patients on chronic ARB or ACE inhibitor therapy had similar or even less severity of disease." (PMID 33681257, 2021). "The unadjusted hazard ratio for suspected/confirmed COVID-19 comparing the ACE inhibitor cohort to the CCB cohort was 0.98 (95% CI 0.72 to 1.32)." (PMID 33722197, 2021). "The cirrhosis-associated abnormalities of ACE, IL-6, VWF antigen, and antiplasmin parallel those observed in severe COVID-19." (PMID 34945736, 2021). "Meanwhile, ACE is a type of metal ion-dependent enzyme with “active pocket” structure, and its inhibiting mechanism is quite similar to that of COVID-19 Mpro and RdRp; all contain an “active pocket or other molecule like metal ion, nucleotide”." (PMID 33671652, 2021). "COVID-19 is spreading globally with the angiotensin converting enzyme (ACE)-2 serving as the entry point of SARS-CoV-2 virus." (PMID 34017843, 2021). "In clinical testing of COVID-19 patients, it was found that the level of angiotensin converting enzyme (ACE) was extremely low." (PMID 34539642, 2021). "Following propensity score matching, 83 individuals (0.44%) in the ACE inhibitor cohort had suspected or diagnosed COVID-19 during 8923 person-years of follow-up, representing a crude incidence rate of 9.30 per 1000 person-years." (PMID 33722197, 2021). "It would also seem that the racial variance of ACE I/D genotype accounts for the different prevalence and outcomes due to COVID-19." (PMID 34834033, 2021). "Before matching, 148 individuals (0.47%) in the ACE inhibitor cohort developed suspected or confirmed COVID-19 during 14,733 person-years of follow-up, representing a crude incidence rate of 10.1 per 1000 person-years." (PMID 33722197, 2021). "The incidence rate of COVID-19 among users of ACE inhibitors and CCBs was 9.3 per 1000 person-years (83 of 18,895 users [0.44%]) and 9.5 per 1000 person-years (85 of 18,895 [0.45%]), respectively." (PMID 33722197, 2021). "Here, we briefly summarize and examine known Alu polymorphisms in ACE, PGR, PLAT, F13B regarding their biological functions, roles in disease, and implications for COVID-19." (PMID 33390179, 2021).
COVID-19 (continued). "In order to successfully defeat the life-threatening COVID-19, many efforts should be made to target ACE, block the cytokines storm, inhibit inflammation, modulate immunity, improve the symptoms, alleviate lung damage, and prevent pulmonary fibrosis." (PMID 35126123, 2021). "The use of ACE inhibitors has been shown to deteriorate symptoms in COVID-19 patients, an observation that has become controversial." (PMID 34674775, 2021). "COVID-19 binding mediated reduction/inactivation of ACE-II can increase ACE/Ang-II signalling pathway and related pathologies." (PMID 32901433, 2021). "The study noted that only 14% of COVID-19 patients with previous exposure to ACE inhibitors either died or had critical illness as compared with 29% of patients without a history of ACEI use." (PMID 33778087, 2021). "It was reported that Lactobacillaceae fermentation produce bioactive peptides with the capability to inhibit ACE likely reducing the concentration of angiotensin II that is responsible for proinflammatory signals in COVID-19 patients." (PMID 33681266, 2021). "It is important to recognise that, to date, no randomised trial evidence exists to demonstrate either benefits or risks of continuing ACE inhibitors or ARBs on the incidence or outcomes of COVID-19." (PMID 33483621, 2021). "Tanama (2020) has reported that seaweeds components appear to counteract the dominance of the ACE/Ang II/ATR1 axis in patients with COVID-19." (PMID 34360741, 2021). "The mechanism underlying this phenomenon is that COVID-19 downregulated the expression of ACE2, causing an imbalance of ACE/ACE2 and an absolute or a relative increase in the Ang II expression level." (PMID 33494713, 2021). "COVID-19 patients who reported smoking (OR: 1.73; 95% CI: 1.02–2.93), alcohol consumption (OR: 2.17; 95% CI: 1.38–3.41), and to be on ACE inhibitors (OR: 5.58; 95% CI: 1.80–17.30) were also more likely to be referred because of disease progression." (PMID 33205749, 2021). "We found reduced ACE serum activity in the DD and ID genotypes of the COVID-19 patients compared to that of the healthy subjects of the same genotyping." (PMID 35095487, 2021). "Further examination of the role of medications that improve kidney function, such as ACE inhibitors, in severe COVID-19 would be worthwhile, with implications for identifying new treatment strategies for severe COVID-19." (PMID 34774005, 2021). "Apart from certain ACE2 genetic variants, insertion–deletion polymorphism in ACE (ACE I/D) may also modulate COVID-19 disease severity by elevating physiological Ang II concentration such that the DD genotype of ACE I/D polymorphism increases the risk of COVID-19 severity." (PMID 34637655, 2021). "ACE inhibitors and angiotensin receptor blockers have been regarded to be beneficial in COVID-19, delaying the binding of SARS-CoV-2 by activating ACE2 and increasing the availability of angiotensin-1–7." (PMID 34943795, 2021). "Both COVID-19 and RA share common mechanistic pathways of pathogenesis mediated through aberrant ACE/ACE2 activities, as well as being driven by the activities of analogous macrophage clusters." (PMID 34943795, 2021). "Discussions revolve around ACE-inhibitors potentially modifying ACE-2 receptors and the effect on the virulence of COVID-19." (PMID 33466289, 2021). "Microginins, the linear peptides, inhibit angiotensin-converting enzyme (ACE), therefore, their use in the treatment of COVID-19 patients with injury of the ACE2 expressing organs is considered." (PMID 33810129, 2021). "ACE D allele was shown to increase expression of ACE2, and the D allele associated with COVID-19 severity as well as frequency of hypoxia in SARS." (PMID 34223911, 2021). "RAS blockers (ACE-inhibitors and II receptor blockers (ARBs)) are a potential component of treatment for COVID-19 patients." (PMID 34853605, 2021).
COVID-19 (continued). "The unadjusted hazard ratio for suspected/confirmed COVID-19 comparing the ACE inhibitor cohort to the CCB cohort (as the reference) was 1.04 (95% CI 0.82 to 1.31), which fell slightly to 1.01 (95% 0.78 to 1.30) after adjusting for measured confounders." (PMID 33722197, 2021). "A combination of ACE inhibitors and calcium channel blockers (CCBs), a critical line of therapy for pulmonary hypertension, has shown therapeutic relevance in COVID-19 when investigated independently." (PMID 33805419, 2021). "Since ACE2 is a functional receptor for SARS-CoV-2, researchers started to carefully consider the safety and potential effects of antihypertension therapy with ACE inhibitors or angiotensin-receptor blockers in patients with COVID-19." (PMID 34016183, 2021). "We reviewed studies surrounding polymorphic Alu retrotransposons in ACE, PGR, PLAT, and F13B that have been either mechanistically linked to and/or associated with clinical conditions relevant to COVID-19." (PMID 33390179, 2021). "To further investigate the signal pathway related to different ACE expressions in COVID-19 patients, we analyzed proteomics profiles of lung and plasma protein alternations in response to COVID-19 under different ACE expressions." (PMID 35095487, 2021). "On the other hand, cirrhotic patients exhibited significantly lower antiplasmin activity and plasminogen activity than COVID-19 patients, while ACE activity and plasma aldosterone concentration were higher." (PMID 34945736, 2021). "This study is aimed at assessing the impact of the angiotensin-converting enzyme (ACE) gene insertion (I)/deletion (D) polymorphisms, on the susceptibility and clinical outcomes of the COVID-19 immunoinflammatory syndrome." (PMID 34603503, 2021). "There is controversy regarding the role of ACE inhibitors or ARBs in potentially increasing the virulence of COVID-19 via the upregulation of ACE2." (PMID 33059711, 2020). "We focused on discovering putative signaling pathways deregulated by Spike-ACE interaction to repurpose available and approved drugs so as to restore the deregulated pathways during COVID-19 treatment (even natural-based products)." (PMID 33363465, 2020). "A quarter of our respondents chose ACE inhibitors as possibly worsening the prognosis of COVID-19 patients, reflecting the early inconsistencies in the published data." (PMID 32748880, 2020). "Given the body of literature surrounding the role of ACE in coronavirus infections, some have suggested using ACE1 inhibitors, such as enalapril and ramipril, and angiotensin receptor antagonists (ARBs), such as candesartan and valsartan, for COVID-19." (PMID 32405877, 2020). "The use of ARNI (angiotensin receptor neprilysin inhibitor) in COVID-19 patients is likely to exhibit the same responses (beneficial/harmful) as ACE/ARB." (PMID 33145103, 2020). "Concerns exist that angiotensin-converting enzyme inhibitors (ACE-i) and angiotensin receptor blockers increase susceptibility to SARS-CoV-2 and the likelihood of severe COVID-19 illness." (PMID 33224428, 2020). "Both RAS and ACE2 play important roles in DM patients with COVID-19, especially through bradykinin being degraded by ACE and angiotensin 1–9 being activated by ACE2." (PMID 33297431, 2020). "The aim of this review is to provide a brief overview of the protective action of GSH against the exacerbated inflammation triggered by COVID-19 upon ACE/ACE2 imbalance." (PMID 32708578, 2020). "These limitations must be considered when using this marker, and a multicenter, prospective cohort study with a larger sample size is needed to validate the role of serum ACE activity in COVID-19." (PMID 33238910, 2020). "Based on these theoretical grounds, intervention studies, either starting or discontinuing ACE inhibitors or ARBs, are currently recruiting patients with COVID-19 (ClinicalTrials.gov)." (PMID 32587077, 2020).